MGMT (O-6-methylguanine-DNA methyltransferase)
Diseases named in the same sentence as MGMT in open-access papers (continued):
Sharing a sentence is not in itself a finding about the gene and the disease.
tumor (continued). "Hypermethylation of multiple genes can occur simultaneously in a tumor, such as APC, DKPK1, MGMT, P16, and RASSF1 in lung cancer, while others, like RASSF1 and P16, could be hypermethylated in a variety of tumors." (PMID 37077808, 2022). "In recent years, studies have attempted to measure MGMT methylation in cell-free DNA (cfDNA) using methylation-specific PCR or pyrosequencing when the tumor tissue is not available." (PMID 34976195, 2022). "We found that the high-risk group was significantly linked to older age, higher tumor grade, the wild status of IDH1, 1p/19q non-codeletion, unmethylated status of the MGMT promoter, and shorter survival." (PMID 36091778, 2022). "As a consequence, the application of TMZ in GBM patients with MGMT-positive tumor tissue is considered unproductive and generally not recommended." (PMID 36551551, 2022). "The PCDHGC3 mRNA expression did not correlate with sex, MGMT promoter methylation, overall survival, tumor growth pattern, localization of tumor, tumor volume, Ki-67-staining, or type of therapy in GBM." (PMID 35897674, 2022). "In the past, we have compared the cytotoxicity of NEO212 and TMZ in a large number of MGMT-negative cell lines from different tumor types, and in all cases we consistently found that the cytotoxic IC50 of NEO212 was significantly lower than the IC50 of TMZ." (PMID 36551551, 2022). "However, the role of MGMT methylation status in regulating tumor immunity in GBM remains to be discussed, and an MGMT methylation-related biomarker should be exploited." (PMID 33614641, 2021). "In the multivariable Cox-regression model with HGG, the cognitive domain memory had significant prognostic value when added to a model which included molecular subtype, MGMT-methylation, the extent of resection, age at diagnosis, KPS, seizures at presentation, and tumor volume." (PMID 34867763, 2021). "The groups of ATL and temporal GTR did not significantly differ in regard of age, sex, tumor localization and MGMT promoter methylation status." (PMID 33554293, 2021). "We cannot definitively conclude that long-term treatment with TMZ in our study resulted in good prognosis regardless of tumor MGMT promoter methylation status." (PMID 34320929, 2021). "Unlike tumor-specific prognostic factors such as the MGMT-methylation status, the extent of resection is a factor that can be controlled by surgeons." (PMID 34621677, 2021). "Treatment‐induced DNA damage in tumour cells with low MGMT levels can therefore no longer be repaired." (PMID 34477324, 2021). "Immunohistochemistry (IHC) staining validated that CD86 expression was correlated with MGMT status and X1p/19q subtypes, which is independent of tumor grade." (PMID 33954112, 2021). "By incorporating low HR capacity (via high %LOH) as a selection criterion in addition to low MGMT and MMR proficiency, we demonstrated the efficacy of the TMZ + ATRi combination in delaying tumor growth and mortality in 2 PDX models, compared to TMZ as a single agent." (PMID 34676045, 2021). "Mg in tumor voxels of patients with MGMT methylation and EGFR amplification was significantly higher than in tumor voxels of patients with MGMT unmethylated tumors and no EGFR amplification with p = 0.02." (PMID 34298788, 2021). "The highest benefit was observed in treated patients with age ≤ 60 years and MGMT methylated tumor, having undergone GTR resection without any evidence of CERTV and BTV." (PMID 34070698, 2021). "If the MGMT gene is silenced by methylation in tumor cells (i.e. MGMT-negative or MGMT-methylated), its DNA repair activity is diminished and the tumor’s sensitivity to chemotherapy is amplified." (PMID 33758290, 2021). "In conclusion, our study reveals a previously undocumented mechanism by which CD90low gaMSCs in the tumour microenvironment contribute to TMZ resistance without dependency on MGMT expression." (PMID 34256854, 2021).
tumor (continued). "The methylation sites and changes in methylation in MGMT’s exon-1 region have been extensively studied in cancer cell lines with and without MGMT expression and in primary tumor specimens." (PMID 33801310, 2021). "OS was associated with the methylation status of MGMT, IDH mutation, pre-surgical KPS score, but not with age, gender, adjuvant chemotherapy cycles (HR:0.628; P:0.159) or the number of lobes with tumor involvement." (PMID 34724914, 2021). "In our investigation, MGMT methylation did not significantly differ between normal mucosa and tumor tissues, arguing against a major role of MGMT in UC-related colon tumorigenesis." (PMID 34680073, 2021). "Different strategies have been applied to overcome MGMT-mediated chemoresistance but none of them have significantly improved tumor progression-free survival." (PMID 33661424, 2021). "PCr/ATP ratio was significantly lower in tumor voxels than in contralateral control voxels in all groups except for MGMT methylated, EGFR not amplified group." (PMID 34298788, 2021). "Gene body methylation and expression of MGMT was lower in tumours within subgroup T2 compared to tumours grouped in T1 and T3 as MGMT methylation was not differentially methylated between these subgroups." (PMID 33536587, 2021). "Third, we identified that tumor TNT are selective because MGMT protein, but not its mRNA, was transferred in vitro and in vivo in GBM and breast cancer." (PMID 34267246, 2021). "Here, we assessed the anti-tumor activity of XH30 in two TMZ-resistant GBM cell lines: one with acquired TMZ resistance and overactivated hedgehog signaling (U251/TMZ) and one with natural TMZ resistance and elevated MGMT levels (T98G)." (PMID 34899305, 2021). "All groups had significantly higher Pi/ATP ratio in tumor voxels compared to contralateral side except for MGMT unmethylated, EGFR not amplified group." (PMID 34298788, 2021). "Regarding PFS, a favorable trend was recorded in cases of younger patients with methylated MGMT and without residual tumor volume but without statistically significant values." (PMID 34070698, 2021). "Overall, there was no statistical difference in counts between tumour core and tumour margin in either MGMT methylated or MGMT unmethylated IDH-wild-type-GBM cases." (PMID 33995529, 2021). "The findings support the notion that low doses of TMZ are effective, provided that the tumor cells are MGMT lacking." (PMID 34944906, 2021). "Due to the significant difference of OS and PFS in patients with MGMT positive and negative methylated tumors, tumor volume was calculated at 3, 6, and 9 months post-op." (PMID 34185258, 2021). "The mPFS in groups with and without MGMT promoter methylation in the tumor was 10.0 months and 11.0 months (p = 0.59), respectively, and mOS was 24.0 months and 18.0 months (p = 0.88), respectively." (PMID 34320929, 2021). "IHC staining validated that CD86 expression was correlated with MGMT status and X1p/19q subtypes, which was independent of tumor grade." (PMID 33954112, 2021). "The levels of CD8+ TILs did not vary significantly according to sex, age, tumor size, tumor resection, Ki-67, MGMT promoter methylation, or postoperative radiotherapy or chemotherapy." (PMID 34646781, 2021). "Recently, a study with a large cohort of matched primary and recurrent IDH-wildtype GBM has shown that MGMT promoter methylation status differs between primary and recurrent tumors, and MGMT methylation status remains predictive for TMZ response in tumor recurrence." (PMID 33628600, 2021). "A quarter (25.2%) of respondents reported that their units did not routinely test MGMT tumour status from the first surgery." (PMID 33791952, 2021). "Another positive point for using metronomic TMZ as salvage treatment is its effectiveness against GBM independent of MGMT status by inhibiting tumor endothelial proliferation." (PMID 32935821, 2020).
tumor (continued). "There was no statistical difference between the presence of the MGMT promoter methylation in the group of patients with pseudoprogression and early tumor progression (p = 0.411)." (PMID 33353180, 2020). "While MGMT promoter hypomethylation is undoubtedly recognized as the primary mechanism of intrinsic TMZ resistance, the genetic alterations acquired during TMZ exposure that contribute to tumor relapse still remain to be fully characterized." (PMID 32753598, 2020). "The third sensitized line 514 was derived from methylated tumor tissue and concordantly exhibited no MGMT expression at baseline." (PMID 32193690, 2020). "The reason may be that MGMT promoter methylated GBMs are more sensitive to alkylating agents, and the application of TMZ can effectively prolong the time for tumor recurrence." (PMID 32922947, 2020). "Retrospective analysis of 15 expansion cohort patients did not demonstrate a correlation between low tumor MGMT expression and patient response, but treatment induced nuclear Rad51 responses in 6 of 12 patients." (PMID 33216844, 2020). "After adjustment for WHO grade, MGMT, Ki67, and TERT, molecular group of IDH1 and ATRX were associated with tumor growth in univariable analysis but not in the multivariable model." (PMID 32388499, 2020). "No MGMT promoter methylation was identified in either tumour and biomarkers that tested positive were identical in both." (PMID 32002804, 2020). "We generated and confirmed at genomic and mRNA levels the BTRC-MGMT and SAR1A-MGMT fusion events in the MGMT-negative patient-derived h543 GBM tumor spheres." (PMID 32753598, 2020). "Other testing showed that the tumor was negative for 1p/19q co-deletion and was O6-methylguanine-DNA methyltransferase (MGMT) promoter unmethylated." (PMID 31748891, 2020). "Multiple genes, such as CDKN2A, DAPK, MGMT, RARB, RASSF1A, and TERT, have been found to be methylated early in lung premalignant lesions, and the level of methylation increases with tumor progression from premalignant lesions to neoplasms." (PMID 32751497, 2020). "Molecular profiling of the tumor tissue of the patient revealed hypermethylation of the O6-methylguanine-DNA-methyltransferase (MGMT) promoter and a negative immunostaining for MGMT." (PMID 32132978, 2020). "Several studies have demonstrated an increase in MGMT activity/expression in the normal/tumor tissue of smokers compared to non-smokers, suggesting the possible role of tobacco smoking in regulating MGMT protein expression in the tissue." (PMID 32324779, 2020). "Tumor or nonmalignant cells can be resistant to TMZ via high levels of MGMT, which repairs the O6-methylguanine (O6-meG) by transferring the methyl group from the O6-meG to its own cysteine residue." (PMID 32599894, 2020). "In the present study, we investigated the promoter methylation levels of MLH1, MGMT, CDKN2A, and RASSF1A in blood and tumor tissue DNA from 69 patients with TAMG, as well as in the healthy thymic epithelial tissue adjacent to the tumor available from 44 of them." (PMID 33192293, 2020). "Therefore, the combination of low tumor MGMT expression and a functional MMR pathway is often considered necessary for TMZ activity, tumor characteristics that only a subset of patients demonstrate." (PMID 33216844, 2020). "Tumor cells lacking MGMT expression are significantly more sensitive to the cytotoxic effects of TMZ than their counterparts expressing functional MGMT." (PMID 32132978, 2020). "We did not observe any significant differences in age, tumor staging, nodal status, cell proliferation, therapy arm or histology type regarding MGMT promoter methylation status." (PMID 32841306, 2020). "However, in hindgut-NETs examined, some cases demonstrated discrepancy between MGMT and GLUT2 status and it would be important to evaluate MGMT and GLUT2 status in tumor cells before administering STZ in GI-NET patients." (PMID 33287738, 2020).
tumor (continued). "The tumor tissues were immunohistochemically examined by using the EnVision detection kit and was found to be negative for MGMT and positive for SDHB, with a Ki-67 index of 1%." (PMID 32132978, 2020). "As DpC and Dp44mT chelate Zn(II), we hypothesized that DpC and Dp44mT decrease MGMT activity by this mechanism and may potentiate TMZ anti-tumor activity." (PMID 33334021, 2020). "Importantly, the MGMT promoter DNA methylation status was preserved between PDOX and parental tumor in all but two PDOXs (online resource)." (PMID 33009951, 2020). "Intriguingly, MGMT expressing tumors had a higher proportion of BCL6-positive cells than the MGMT-negative tumours." (PMID 32320427, 2020). "However, O6-methylguanine-DNA methyltransferase (MGMT/AGT) can repair such DNA alkylation damage, thereby leading to tumor resistance." (PMID 33187214, 2020). "Both studies revealed that OS was significantly correlated with the MGMT methylation status of the primary tumor, but not at relapse, therefore showing no implication towards repetitive MGMT methylation testing in tumor recurrence." (PMID 31766430, 2019). "At univariate analysis ECOG-PS (0/1 vs ≥ 2), sex (female vs male) and extensive tumor resection showed to be significantly related to a longer PFS, while MGMT expression ≥70% to a shorter PFS; multivariate analysis only ECOG-PS was confirmed as an independent predictor for PFS." (PMID 30678211, 2019). "They found higher degree of methylation of MGMT, RARβ, RASSF1A, and CDH13 in tumour specimens and of SOCS-1 in peripheral blood with higher levels of IL-6, while others found less degree of methylation of USP2, TMEM49, SMAD3, DTNB, and IL-6 promoter with higher levels of IL-6." (PMID 31205673, 2019). "Articles on different tumor entities, not providing data on MGMT promoter methylation, without information on MGMT promoter methylation of primary tumor and relapse or describing unmatched primary tumor and relapse samples were excluded." (PMID 31766430, 2019). "The assay assesses 5 CpG sites within exon 1 of the tumour suppressor gene MGMT, and interrogates a cytosine nucleotide not followed by a guanine in exon 1 to determine bisulfite conversion." (PMID 31652288, 2019). "Because only one tumor showed the molecular signature IDH-mutated and MGMT not methylated this variant was not further evaluated." (PMID 31623667, 2019). "They conclude that the MGMT promoter methylation status does not change from primary to recurrent tumor in the vast majority of GBM patients and due to this fact they see no implication for repetitive testing in daily clinical routine." (PMID 31766430, 2019). "Patients with newly diagnosed GBM will invariably receive the standard care of radiation therapy and TMZ after surgical removal of the tumor regardless of their expression status of MGMT." (PMID 31726966, 2019). "The almost similar levels of MGMT promoter methylation between GBM and GSCs suggested that also this epigenetic marker is conserved in the GSC population, which is usually responsible for the high frequency of recurrence in this type of tumour." (PMID 30984267, 2019). "In our cohort, MGMT promoter methylation was present in 14% of patients and was independent of age, sex, tumor location, radiographic appearance and EOR." (PMID 31362435, 2019). "In 5 seronegative patients, anti‐MGMT‐02 peptide autoantibody level remained seronegative; not only 30 days postoperatively but also when tumor recurred." (PMID 31210005, 2019). "The MGMT promoter methylation of the parent tumor status was not concordant with the clustering as the two most sensitive tumors and two of the four least sensitive tumors were MGMT promoter methylated." (PMID 31238897, 2019).
tumor (continued). "Similar to previous reports, MGMT was methylated and multiple DNA MMR genes (MLH1 and PMS2) were mutated in the recurrent tumor, but these variants were not present at diagnosis." (PMID 29487696, 2018). "As shown, tumor tissues from vehicle-treated animals (A1, A2, M1, M2) are MGMT-negative, just like their in vitro-cultured counterparts (shown on the left side of the blot)." (PMID 30274152, 2018). "The results in toto suggest that MR30 is the first prototype of agents that may be used against tumours addicted to EGFR and to sensitize resistant tumours co-expressing EGFR and MGMT to TMZ." (PMID 30416678, 2018). "Half of the patients (n = 30) had MGMT promoter methylation, and 13 patients showed ATRX mutation, while none of patients had 1p/19q co-deleted tumor." (PMID 30375429, 2018). "However, O6-methylguanine DNA-methyltransferase (MGMT, a DNA repair enzyme) can remove these methylations, and tumor cells overexpressing MGMT display pronounced resistance to TMZ." (PMID 30651933, 2018). "Tumor location was significantly different between MGMT promoter methylated and unmethylated groups (P = 0.012), implying that the subventricular zone (SVZ) was more likely to be spared in patients with MGMT promoter methylation." (PMID 29467012, 2018). "To date, conventional structural image features, including tumor location, tumor volume, enhancement, invasiveness, and edema, have been utilized to predict the MGMT promoter methylation, however without expert consensus." (PMID 29467012, 2018). "A three-gene panel (MGMT, RASSF1A, SEPT9) identified malignancy with 96.6% sensitivity, 74.0% specificity and 91.5 positive predictive value (area under the curve: 0.97), independently of tumor location, stage, and molecular pathway." (PMID 29486770, 2018). "Such a type of molecules could be used alone in tumours addicted to EGFR or to enhance the benefit of TMZ-based chemotherapy in tumours co-expressing EGFR and MGMT." (PMID 30416678, 2018). "In clinical routine, negative MGMT expression was found the most reliable predictive marker for tumor response to TMZ." (PMID 29344904, 2018). "While potentiation of TMZ treatment can be enhanced by inhibiting the mechanisms behind drug resistance, novel approaches to inhibit the effects of MGMT, BER, and MMR, that invariably arm tumor cells with the ability to combat TMZ activity, must be developed and implemented." (PMID 29963012, 2018). "Moreover, this regulation occurred independently from MGMT promoter methylation status, offering a probable target to reestablish chemosensitivity to TMZ in tumor that developed chemoresitance." (PMID 29558958, 2018). "Increased MGMT expression level is exclusively a tumor phenotype trait as MGMT levels in normal tissues do not vary between patients with benign or malignant disease." (PMID 30038716, 2018). "The therapeutic resistance to TMZ can occur at different levels, and it may be related to the enzyme O-6-methylguanine-DNA methyltransferase (MGMT), whose expression varies widely in different kinds of tumor cells." (PMID 30441761, 2018). "In addition, our study correlated the decrease of tumor volume induced by the miRNA-370-3p/TMZ treatment with the decrease in FOXM1 and MGMT (i.e., two targets of miR-370-3p)." (PMID 30497054, 2018). "In this study, we have shown that NEO412, a conjugate derived from TMZ, linoleic acid and POH displays significant anti-tumor activity regardless of MGMT status, and displays no overtly observable side effects." (PMID 30651933, 2018). "The proportion of MGMT promoter hypermethylation ranged from 3.0% to 70.1% (median: 24.8%) in tumor tissues and 0.0% to 36.9% (median: 0.3%) in non-cancerous controls, respectively." (PMID 28986566, 2017). "Survival is significantly worse for patients whose tumor is unmethylated at the O6-methylguanine-DNA methyltransferase (MGMT) promoter because they do not respond to DNA damaging therapy." (PMID 28314386, 2017).